EZH2 (enhancer of zeste 2 polycomb repressive complex 2 subunit)
Diseases named in the same sentence as EZH2 in open-access papers (continued):
Sharing a sentence is not in itself a finding about the gene and the disease.
tumor (continued). "A previous study showed that PVT1 can increase the expression of miR-214 by enhancing the binding of enhancer of zeste homolog 2 (EZH2) to the miR-214 promoter, which ultimately promotes tumor cell proliferation and invasion." (PMID 31380270, 2019). "In vivo, we found that, in the glucose group, xenograft tumors derived from si-SLC34A2 cells were markedly smaller than those from si-NC cells, whereas co-infected with p-EZH2 and si-SLC34A2 resulted in restored tumor volume." (PMID 30038060, 2019). "Thus, we speculated that EZH2 might be involved in tumor-promoting functions of SNHG6." (PMID 30626446, 2019). "SMYD2, EZH2, and SUV420H2 were up‐regulated and SETD7, PRDM1, PRDM8, PRDM6, and PRDM5 were down‐regulated in tumor." (PMID 30984543, 2019). "The apparently conflicting functions of EZH2 in cancer may therefore simply reflect the antithetic roles that the protein plays at distinct stages of the disease: tumour suppressor during tumour‐initiation, and tumour‐promoter after cells transform and reprogramme their epigenome." (PMID 31468686, 2019). "For this, we examined EZH2 expression level in clinical PTC tissue and found that it is higher in tumor tissues." (PMID 31718595, 2019). "The roles of MALAT1, EZH2 and ABI3BP in the development of GBC were further explored through xenograft tumor in nude mice." (PMID 31174563, 2019). "Furthermore, the combination of either CDK2 or EZH2 inhibitor with tamoxifen effectively suppresses tumor growth and markedly improves the survival of the mice bearing TNBC tumors, suggesting that the mechanism-based combination therapy may be an alternative approach to treat TNBC." (PMID 31704972, 2019). "After the average tumor volume reached 200 mm3, we randomly divided mice into 4 groups for i.p injections of the control DMSO, Enz (30 mg/kg) and/or EZH2 inhibitor-Dznep (1 mg/kg) every other day." (PMID 31189930, 2019). "However, the discovery of EZH2 inhibitors and BRD9 inhibitors as possible therapeutic approaches for some cancers with BAF subunit mutations, illustrates why the comprehension of the precise mechanism by which subunit mutations result in tumour growth, is so important." (PMID 30898143, 2019). "By binding to the specific 36G46A micro-domain of HOTAIR, ADQ efficiently abrogate the HOTAIR/EZH2 interaction, thereby inhibiting H3K27-mediated tri-methylation of the NLK and consequently inhibiting tumor metastasis." (PMID 30764859, 2019). "We also performed Western blot analyses to detect the levels of CDYL, EZH2, and CDKN1C in xenograft tumours, and GSK126 significantly increased CDKN1C levels in CDYL-overexpressing H69 cells, but did not significantly change CDYL levels." (PMID 31367252, 2019). "miR-101 has been reported to act as a tumor suppressor by targeting CDH1 inhibitors, such as ZEB1/ZEB2 and EZH2 in different tumors, including GC." (PMID 31509966, 2019). "When mice eventually succumbed, the tumor was isolated from the brains and the amount of BMI1, EZH2, and LSD1 proteins in the treated tumors was compared against those of untreated tumors, confirming a significant increase for all three proteins." (PMID 30683859, 2019). "In zebrafish xenografts, genetic and pharmacological knockdown of EZH2, through molecules such as GSK503 or UNC1999, reduces tumor growth and colony formation of CjM cells." (PMID 31683701, 2019). "To verify that UCA1 regulate EZH2 and CDK6 expression through sponging miR-26a and miR-26b, we first quantified the EZH2 and CDK6 protein level in tumour and control tissues by immunoblotting." (PMID 31272462, 2019).
tumor (continued). "Apoptosis marker cleaved caspase‐3 IHC staining of these subcutaneous tumours displayed that enhanced expression of LINC01535 suppressed HeLa cell apoptosis in vivo, which was also reversed by miR‐214 overexpression or EZH2 silencing." (PMID 31273925, 2019). "Next-generation sequencing revealed loss of heterozygosity with very high allelic frequency in NOTCH3, TGFB1, EZH2 and KMT2C in the patient tumor, the subcutaneous PDX and the PDOX." (PMID 31732509, 2019). "Knockdown or pharmacological inhibition of EZH2 in ARMS cells leads to apoptosis and reduced tumor growth of ARMS xenografts in vivo." (PMID 31970591, 2019). "Here, the authors show that the tyrosine kinase c-Src stimulates mitochondrial function to signal energy sufficiency to mTORC1, increasing translation of the PRC2 subunits EZH2 and SUZ12 to support ErbB2-dependent tumours." (PMID 31263101, 2019). "Loss of heterozygosity (LOH) with very high allelic frequency was observed in NOTCH3, TGFB1, EZH2 and KMT2C in the patient tumor, the subcutaneous PDX and the PDOX." (PMID 31732509, 2019). "Crucially, the molecular pathways promoting EZH2/PRC2 overexpression are incompletely understood, despite their potential importance in mediating epigenetic dysregulation and tumor progression in these cancers." (PMID 31263101, 2019). "Notably, three of the ranked apoptosis-regulating genes (DAB227, DLC128,29, and NOXA30) are known tumor suppressors that are implicated in suppressing proliferation and promoting apoptosis, i.e., the phenotypes we observed when CARM1 was knocked out or EZH2 activity was inhibited with GSK126 (, 2)." (PMID 29434212, 2018). "Modulating EZH2 expression or activity suppressed phosphorylation of certain RTK, restoring the anti-tumor effects of sunitnib." (PMID 29556394, 2018). "To validate the relationship between EZH2 and FOXC1, we first quantified FOXC1 protein levels in 20 Luminal B patient tumour samples via immunofluorescence staining of breast tissue biopsies." (PMID 29959321, 2018). "In contrast, our data clearly demonstrate that EZH2 inhibition can suppress the growth of CARM1-expressing tumors and improves survival of tumor bearing mice." (PMID 29434212, 2018). "Our results identified a feedback loop of miR-6868-5p/FOXM1, in which miR-6868-5p inhibits tumor angiogenesis by suppressing FOXM1-IL-8 axis, and in turn FOXM1 downregulates miR-6868-5p by stimulating EZH2-mediated transcriptional suppression of miR-6868-5p." (PMID 30486864, 2018). "In our study, EZH2 was over-expressed and its higher expression predicted longer survival time for LUSC patients, indicating its potential tumor suppressor role in LUSC." (PMID 30367091, 2018). "Active EZH2 induces and activates, in conjunction with HMGA, tumour-promoting factors and proliferation, repressing differentiating factors such as runt-domain transcription 3 factor (RUNX3), p57 cyclin-CDK inhibitor 1C (CDKN1C), and cadherin 1 (CDH1)." (PMID 29853899, 2018). "Alterations in epigenetic regulators such as enhancer of zeste 2 (EZH2, a regulator of H3K27 methylation) have a global influence on both tumorigenesis and drug sensitivity in various tumor models." (PMID 29712898, 2018). "Similar to the results observed in smoking patient samples, immunohistochemistry in tumor sections of NIC-treated (0.25 mg/kg body weight, 80 days) mice showed 30% enhanced EZH2 expression." (PMID 29396474, 2018). "Taken together, our study systemically elaborated the molecular network of miR‐144‐3p and EZH2 in LUAD and provided a deeper understanding of the tumor biology in LUAD." (PMID 30280514, 2018). "Tumor production of the T helper 1 (Th1)-type chemokines CXCL9 and CXCL10 is epigenetically repressed by EZH2-mediated H3K27me3 and DNMT1-mediated DNA methylation in EOC." (PMID 29482595, 2018). "We found that EZH2 and galectin-9 expression levels were up-regulated after IFN-γ stimulation in HCC, changes that we surmised are instrumental in modulating the tumor microenvironment." (PMID 29316949, 2018).
tumor (continued). "Interestingly, Ezh2-deficient tumours assessed for H3K27me3 by immunofluorescence at endpoint exhibited undetectable levels of H3K27me3 in the tumour epithelium, indicating that Ezh1 was not able to compensate for the loss of Ezh2 histone methyltransferase activity." (PMID 29959321, 2018). "It has been reported that EZH2 can attenuate expression of TIMP-2 and TIMP-3 by inducing gene promoter DNA methylation, thereby increasing MMP activity in tumor cells." (PMID 30341286, 2018). "However, how the dysregulated EZH2 in TAM participates tumor progression is still unknown." (PMID 29556394, 2018). "EGCG suppressed cancer stem cell generation by decreasing the expression of the subunits of the polycomb repressive complex, EZH2, and SUZ12, and the levels of tumor suppressor miRNAs miR-34a, miR-145, and miR-200c." (PMID 30627525, 2018). "We also tested the effect of β-elemene in NPC tumor growth and DNMT1, EZH2 expression in nude mouse xenografted cancer model." (PMID 28360411, 2017). "Reports showed that EZH2 inhibitors, such as suberoylanilide hydroxamic acid (SAHA) and 3-deazaneplanocin A (DZNep), exerted anticancer effects through activation of tumor-suppressor microRNAs (miRNAs) in gastric and liver cancer cells." (PMID 28360411, 2017). "To evaluate the impact of Ezh2 in CD8+ T-cell responses, we used an experimental ACT model, of which transferred T cells were more effective in controlling tumor growth in lymphopenic mice compared with lymphoreplete hosts." (PMID 29242551, 2017). "Consistent with this, β-elemene inhibited tumor growth, phosphorylation of Stat3, expressions of DNMT1 and EZH2 in a mouse xenograft model." (PMID 28360411, 2017). "Due to this, EZH2, which is the core member in PRC2 complex, was found to be required for the DIPG growth and it inhibitor had the effect on the tumor transplanted to the mice model." (PMID 29118968, 2017). "For example, miR-26a inhibits epithelial–mesenchymal transition (EMT) function and up-regulates tumor suppressor genes, DAB2IP and RUNX3, through post-transcriptional repression of EZH2 in human hepatocellular carcinoma and lung carcinoma cells in vitro." (PMID 28561778, 2017). "The pattern of high EZH2, but low H3K27me3 mark, is also prevalent in human lung SCC and SCC regions within ADSCC tumours." (PMID 28387316, 2017). "Enhancer of zeste homolog 2 (EZH2) is the core structural component of polycomb repressive complexes 2 (PRC2), which can silence tumor suppressor genes through methylating lysine 27 of histone 3 (H3K27)." (PMID 27880940, 2017). "miR-200b had been found to suppressed cell EMT process and functioned as a target of EZH2, such as, DNMT1 and EZH2 mediated methylation silences the microRNA-200b/a/429 gene and promotes tumor progression." (PMID 28615992, 2017). "EZH2 was initially shown to have oncogenic functions; however, many studies in recent years has shown that PRC2 also has tumor suppressive effects in cancer." (PMID 29212262, 2017). "This study firstly demonstrated that miR-193a acted as tumor suppressor in CRPC and the autoregulatory feedback loop of HOTAIR/EZH2/miR-193a served an important mechanism in PCa development." (PMID 29141691, 2017). "In contrast, histone lysine methyltransferases (KMTs) like EZH2 rely on a steady supply of S-adenosyl methionine (SAM, PubChem CID: 9865604) utilized for histone tri-methylation leading to repression of tumor suppressors." (PMID 28265786, 2017). "For example, the tumor suppressive gene, DAB2 interacting protein (DAB2IP) was inhibited by EZH2/PRC2." (PMID 28264478, 2017).
tumor (continued). "In the study, we found that EZH2 inhibition by UNC1999 resulted in the upregulation of 118 microRNAs, of which many have been identified as downregulated tumor suppressor microRNAs in MM." (PMID 28664185, 2017). "EZH2 positively regulates MMSET expression at the post-transcriptional level by repressing the expression of miR-26a, miR-31 and miR-203, thus promoting tumor development." (PMID 26497210, 2016). "We found, for example, that even after strict false discovery rate (FDR) correction, EZH2 and AURKB levels showed robust positive correlation with triple negative (TN) malignancies and high Ki67 index, as expected from their role in tumor aggressiveness." (PMID 27863398, 2016). "DIM promoted the expression of the let-7 family, while it reversed the tumor progression and EMT by preventing ZEB1, and it conducted the reduction of enhancer of zeste homolog 2 (EZH2) intervening in EMT phenotypic cells." (PMID 27231938, 2016). "In support of this, we observed modulation of other pathways that would predict sensitivity to EZH2 inhibition, including increased CDKN2A, which is both a known target of PRC2/EZH2 as well as a tumor suppressor." (PMID 27391784, 2016). "As we had determined EZH2 protein expression on the similar cohort, we analysed the expression of HELLS and EZH2 in similar tumor areas." (PMID 27191985, 2016). "Specifically, EZH2 is significantly overexpressed in MDS and AML primary tumor cells that display aberrant DNA methylation of the gene encoding the tumor suppressor p15INK4B compared with tumors where p15INK4B is not methylated." (PMID 26497210, 2016). "Linc-POU3F3 is increased in ESCC samples, which, through interactions with EZH2 to promote methylation of POU3F3, then promote tumor development." (PMID 26974151, 2016). "EZH2 can induce EMT of prostate cancer cells by down-regulation of DAB2IP, a tumor-suppressive Ras GTPase-activating protein (RasGAP)." (PMID 26623562, 2016). "As an initial step to investigate the potential role of EZH2 in OPSCC, we compared the RNA expression of EZH2 in a panel of randomly selected HPV+ and HPV- patient tumor samples." (PMID 27793210, 2016). "The oncogenic function of EZH2 may be augmented by the methylation-dependent degradation of tumour suppressive proteins such as RORα in cancer, thus providing an attractive prototype, suggesting the cross-regulation of oncogenes and tumour suppressor genes for efficient tumour progression." (PMID 26757928, 2016). "This miRNA has been described as a tumor suppressor that inhibits the expression of oncogenes, such as RAB GTPase 5A (RAB5A) and enhancer of zeste 2 (EZH2)." (PMID 26895946, 2016). "On the contrary, EZH2, EED and SUZ12 were substantially overexpressed in tumor samples (n = 22, p < 0.01)." (PMID 27472460, 2016). "In all tumor types, differentially methylated CpGs were highly enriched in binding sites of polycomb-related SUZ12, EZH2 and CTBP2, and the enrichment rate strongly correlated with the degree of CGI methylation." (PMID 26464434, 2016). "In summary, we uncover a TET1/GFI1/EZH2/SIN3A⊣miR-22⊣CREB-MYC signalling circuit in de novo AML, in which miR-22 functions as a pivotal anti-tumour gate-keeper, distinct from its oncogenic role reported in MDS or MDS-derived AML16." (PMID 27116251, 2016). "The Ezh2 expression level was elevated in ESCC patients in line with WHO stage and predominantly up-regulated in late-stage tumor tissues (P=0.0221, P=0.0302)." (PMID 27015363, 2016). "Consistent with this, PPI inhibited tumor growth, protein expression levels of p65, DNMT1 and EZH2, and increased phosphorylation of SAPK/JNK in vivo." (PMID 27421653, 2016).
tumor (continued). "EZH2 inhibitor DZNep has been shown to enhance the treatment effect of gemcitabine in PDA cell lines and PDA primary tumor cell cultures." (PMID 27999365, 2016). "Enhancer of zeste homolog 2 (EZH2) is a candidate oncogenic driver due to its prevalent overexpression and aberrant repression of tumor suppressor genes in diverse cancers." (PMID 26868841, 2016). "According to these findings in multiple malignancies EZH2 mediates the activation of EMT program, which is a known mechanism inducing tumor aggressiveness and metastasis." (PMID 27793053, 2016). "Most importantly, PRC2, and specifically the EZH2 and SUZ12 subunits, have been shown to regulate miR-200b in the context of neoplasia." (PMID 25884496, 2015). "EZH2 is the core component of the PRC2 complex, which mediates the transcriptional repression of pro-differentiation genes in both normal and tumor cells." (PMID 25823657, 2015). "Together, these results suggested that DZNep inhibited the EZH2/KPNB1 signaling pathway and MPNST xenograft tumor growth in mice." (PMID 25890085, 2015). "A xenograft tumor model was used to confirm that EZH2 depletion inhibited HNSCC cell growth and induced tumor cell apoptosis." (PMID 26378043, 2015). "We investigated the effects of an EZH2 inhibitor, 3-deazaneplanocin A (DZNep), on MPNST cell cycle, survival and apoptosis in vitro and on MPNST xenograft tumor growth in vivo." (PMID 25890085, 2015). "Immunoblot and immunohistochemical analyses showed that DZNep downregulated EZH2/KPNB1 signaling in vivo, thereby inhibiting MPNST tumor cell proliferation, and induced cell death." (PMID 25890085, 2015). "From these studies we conclude that EZH2 GOF mutants maintain enhanced histone methyltranferase activity in vivo and that this activity correlates with increased tumor growth." (PMID 25671303, 2015). "In contrast, miR-30a and miR-145, which are suggested to act as tumor and/or EMT suppressors, are upregulated by EZH2 silencing, and are repressed upon EZH2 overexpression, in agreement with others." (PMID 26517683, 2015). "Inversely, in non-invasive tumor cells miR-31 targets SOX4, EZH2 and HDAC3 by direct and indirect means to inhibit tumor cell invasion." (PMID 25644061, 2015). "This is interesting because EZH2 is the major methyltransferase component for PRC2 and has been demonstrated to regulate miR-200b in neoplasia." (PMID 25884496, 2015). "Our intracranial mice model also revealed delayed tumor growth in HOTAIR siRNA- and EZH2 inhibitor-treated groups." (PMID 25428914, 2015). "To confirm the depletion of EZH2 in MPNST xenograft tumors by DZNep treatment in vivo, we conducted Western blot analyses of EZH2 and KPNB1 protein expression in two xenograft tumor samples randomly selected from each group." (PMID 25890085, 2015). "Previous studies have demonstrated EZH2 can decrease DAB2IP expression and E2 can increase EZH2 through ERs and tumor progression." (PMID 26587829, 2015). "Combination of etoposide with Ezh2 inhibition results in greater accumulation of DNA-DSB and cell death, resulting in superior anti-tumor activity and therapeutic efficacy with minimal acute toxicity in vivo." (PMID 25605014, 2015). "It interacts with EZH2, SUZ12, and the PRC1 subunit CBX7 (ADP Ribosylation Factors) mediating the silencing of p16INK4a, p15INK4b and p14ARF tumor suppressors through the recruitment of PRC2 and PRC1." (PMID 26580594, 2015). "Comparing with normal mucosa or adjacent normal tissue, EZH2 was overexpressed in 50-60% of HNSCC tissues and contributed to tumor differentiation status." (PMID 26378043, 2015). "As crucial tumor promoters and oncogenes, EZH2 and DNMT1 are highly expressed in a wide range of cancer types and overexpression of EZH2 and DNMT1 are correlated with advanced stages of cancers, resulting in poor prognosis." (PMID 26362062, 2015). "Recently, Ezh2 inhibition by compounds such as DZNep and GSK126 has proven to display in vitro and in vivo anti-tumor activity." (PMID 25605014, 2015).